IGFBP2 (insulin like growth factor binding protein 2)
Diseases named in the same sentence as IGFBP2 in open-access papers (continued):
Sharing a sentence is not in itself a finding about the gene and the disease.
glioma (continued). "We also sought to determine by immunohistochemistry whether glioblastoma multiforme (GBM) cases, the most aggressive type of glioma, express ADAMTS1 and produce both the intact and the cleaved forms of IGFBP2." (PMID 24962328, 2014). "Furthermore, we also found that the luciferase activities showed no significant change with mutant binding site of IGFBP2 in glioma cells after HOTAIRM1 down-regulation." (PMID 38012763, 2023). "IGFBP2 has been reported to exert an oncogenic effect by enhancing invasiveness, angiogenesis, and VM formation and as part of a negative feedback loop with HIF1α in glioma." (PMID 32765489, 2020). "Furthermore, each of these genes is prognostic in overall gliomas; however, within the IDH-mutant group, none remains prognostic except IGFBP2 (encodinginsulin-like growth factor binding protein 2)." (PMID 27852048, 2017). "No study has focused on the regulatory mechanisms of the IGFBP2 gene, particularly in glioma." (PMID 28323865, 2017). "Thus, there exists a link between IGFBP2 and glioma cell growth independent of its effects through the binding of IGFI and the blocking of IGFIR activation." (PMID 25884993, 2015). "However, other genes usually related to gliomas such as VEGF or IGFBP2 were not present in the first triples." (PMID 17519038, 2007). "In addition to our knowledge, we found one of the molecular mechanisms of SVIP-controlled PTENwt-dependent IGFBP-2 regulation in glioma, which provides the basis for IGFBP-2 as a marker indicating PTEN status, tumor progression, recurrence and survival of high-grade glioma." (PMID 39138166, 2024). "Notably, a recent study indicated that IGFBP2 may act as a stimulator of VM formation by upregulating MMP2 expression in glioma cells, indicating that activation of MMPs might be essential for VM formation in glioma." (PMID 36708044, 2023). "Furthermore, these analyses detected the cleaved form of IGFBP2, showing a statistically significant correlation between the levels of this processed form with that of ADAMTS1, which supports our hypothesis that ADAMTS1 cleaves IGFBP2 in glioma." (PMID 24962328, 2014). "We revealed that only SRSF1, but not IGFBP2 and EMP3, was markedly reduced by miR-6760-5p mimics but increased by miR-6760-5p inhibitors in glioma tumor cells, suggesting that SRSF1 is the direct target of miR-6760-5p." (PMID 37063420, 2023). "Furthermore, DEGs exclusively detected at grade IV with large FC values (i.e., IGFBP2 and GABRA5) revealed huge variation in expression levels compared to previous grades, which was speculated to be closely correlated with the significant changes during the development of glioma into glioblastoma." (PMID 25845910, 2015). "To validate the protein-level expression patterns of the prognostic genes in clinical specimens, we performed immunohistochemical (IHC) staining of MAOB, IGFBP2, SERPINA1, and LGR6 on paraffin-embedded sections of glioma tissues and adjacent non-tumorous brain tissues." (PMID 40821817, 2025). "IGFBP2 carries Arg-Gly-Asp (RGD) domain that binds to integrins like α5β1 for glioma cell migration, while RGD → RGE mutant (D306E) IGFBP2 could not interact directly with integrin α5 resulting in losing cell mobility." (PMID 31560714, 2019). "However, IGFBP-2 is not highly expressed in all GBMs with poor prognosis, and IGFBP-2 expression in glioma tissues is not a suitable marker for prognosis prediction." (PMID 24690948, 2014). "Since Igfbp2 is known to be upregulated in glioma cells, the reported downregulation in MTLE samples may reflect a relative decrease compared to glioma tissue, rather than true reduction relative to healthy hippocampal levels." (PMID 41239819, 2026).
Obesity (84 papers, 2010 to 2026). Accumulation of substantial excess body fat. "In some animal studies, early-life hypermethylation of the IGFBP2 promoter and reduced IGFBP2 expression were linked to disrupted glucose regulation, obesity, and liver fat accumulation later in life." (PMID 41333061, 2025). "Recent studies have demonstrated that suppression of IGFBP2 expression mitigates FGF1-induced activation of AMPK, supporting a critical role for IGFBP2 in mediating the therapeutic effects of FGF1 on obesity-associated hepatic steatosis." (PMID 40608848, 2025). "Higher IGFBP-2 levels are linked to a favorable metabolic profile, characterized by reduced visceral fat accumulation and a decreased risk of obesity and insulin resistance." (PMID 39585162, 2024). "Another obesity-associated gene upregulated in mice data was IGFBP2, which was also confirmed in published human datasets." (PMID 38918843, 2024). "Specifically, we found off-target C-to-T editing in obesity mice generated premature stop codons and non-synonymous mutations on obesity and metabolic disorder-associated genes, e.g., Igfbp2, C3, Apoe, and Apoc3." (PMID 36997536, 2023). "High-serum IGFBP2 is associated with a decreased risk of diabetes, playing a protective role against insulin resistance and obesity." (PMID 37436978, 2023). "Low serum IGFBP2 concentration is associated with a higher risk of obesity-related insulin resistance." (PMID 36140769, 2022). "In children with obesity the reduced levels of circulating IGFBP2 were found to increase after 6 and 12 months of weight loss although they were not completely normalized, most likely because a normal body weight was not yet achieved." (PMID 34975768, 2021). "Recent studies show solid association between mRNA and serum IGFBP2 and metabolic disorders, including obesity, metabolic syndrome, insulin resistance, and type 2 diabetes, as detailed below." (PMID 33498859, 2021). "The proteins with the largest effect estimates were leptin and IGFBP2, both of which have been previously reported to be associated with obesity, T2D and MetS." (PMID 34016094, 2021). "In experimental studies mice overexpressing Igfbp2 have been reported to have lower susceptibility to develop obesity, insulin resistance and increased blood pressure." (PMID 34835949, 2021). "We provide an update of the association between low serum IGFBP2 and an increased risk of obesity, metabolic syndrome, type 2 diabetes, as well as insulin resistance." (PMID 33498859, 2021). "In mice susceptible to the development of diet-induced obesity, Igfbp2 is hypermethylated and transcriptionally suppressed prior to the development of hepatic steatosis and this is stable over time." (PMID 31389294, 2020). "Diabetes in mouse models of insulin resistance, insulin deficiency, and obesity can be reversed by the overexpression of Igfbp2 and, in contrast, mice harboring a mutation in Lep become obese and diabetic." (PMID 33031577, 2020). "Overexpression of IGFBP-2 was associated with decreased susceptibility to obesity and improved insulin sensitivity." (PMID 32380764, 2020). "IGFBP-2 concentration has been associated with improvements in insulin sensitivity, BMI and lipid profile in obesity-related studies." (PMID 32586279, 2020). "We have shown that mice over expressing human IGFBP-2 have a reduced susceptibility to obesity and also improved insulin sensitivity." (PMID 30392760, 2019). "We have presented in this study that C/EBP-α, FOXO1, PPAR-γ2 and IGFBP-2 have an interesting association in insulin resistance associated with obesity: their expression profile was found altered in adipose tissue in an insulin-dependent manner." (PMID 31547433, 2019). "Further, we determined the PPAR-γ2–RXR-α heterodimer activity in VAT, especially its interaction on the IGFBP-2 promoter to test its association with obesity and insulin resistance." (PMID 31547433, 2019).
Obesity (continued). "IGFBP-2 is the abundant in blood, and has been shown to play a role in preventing insulin resistance and diet-associated obesity in mice." (PMID 27009398, 2016). "Changes in IGFBP-2 levels are associated with various physiological and pathological states, such as exercise, pregnancy, aging, hormones, diabetes, obesity, insulin resistance and tumours." (PMID 25695641, 2015). "The association of obesity with risk is thought to be mediated by elevated circulating estradiol levels; IGFBP-2 has been shown to be inversely associated with serum estradiol." (PMID 26106415, 2015). "Potentially counterbalancing the proliferative effect of IGFBP-2 is the observation that serum IGFBP-2 levels are inversely associated with obesity." (PMID 26106415, 2015). "Furthermore, in a small cohort of patients with obesity, it was observed that the plasma level of IGFBP2 is inversely associated with the hepatic fat fraction." (PMID 40608848, 2025). "Thus, obesity is a confounding factor for the association of serum IGFBP-2 with markers of COVID-19 disease severity." (PMID 38255230, 2024). "Although many studies have shown associations between IGFBP-2 and NAFLD in obesity, the present observations suggest that low plasma IGFBP-2 levels can indicate a higher risk for the development of NAFLD in asymptomatic, apparently healthy individuals with higher VAT." (PMID 37854178, 2023). "Moreover, circulating IGFBP-2 levels are associated with reduced insulin sensitivity in obesity patients, and the decrease in IGFBP-2 post-surgery indicates an increase in insulin sensitivity." (PMID 35159232, 2022). "Notably, overexpression of IGFBP2 in mice also revealed positive effects on glucose metabolism that where linked with obesity and were identified only at older ages." (PMID 36353242, 2022). "We finally review the main risk factors that are associated with low serum levels of IGFBP2, since these factors may be considered for the prevention strategies and treatment of obesity-related insulin resistance." (PMID 33498859, 2021). "ADIPOQ and IGFBP2 were reported before to be associated with T2D and obesity." (PMID 34016094, 2021). "We hypothesize mechanisms by which IGFBP2 could be implicated in the development of obesity and insulin resistance as well." (PMID 33498859, 2021). "Female mice were more delayed in developing significant weight gain and some of the associated modifications such as IGFBP2 levels might also be more delayed compared to males, while the patients with changes in this binding protein had more long-term obesity." (PMID 34975768, 2021). "The susceptibility to diet-induced obesity and its metabolic complications differs between the sexes and this could be related to the differential changes in IGFBP2." (PMID 33202914, 2020). "Contrary to negative correlation, most TSGs that positively correlated with promoter methylation were not functionally enriched in the GSEA, although some of them, such as IGFBP2, had associations with diabetes, insulin resistance, insulin sensitivity, and obesity." (PMID 32709145, 2020). "For instance, the activation of PPAR-γ2, which cannot be blocked by FOXO1, may up-regulated IGFBP-2 expression to protect adipocyte cells towards metabolic alterations associated with obesity." (PMID 31547433, 2019). "In addition, IGFBP-2, the mostly highly accumulated from C5aR1−/− adipocytes, is associated with reduced susceptibility to obesity and improved insulin sensitivity, further supporting the injurious role of C5aR1 in adipose inflammation and dysfunction." (PMID 30294325, 2018). "In particular, low circulating concentrations of IGFBP2 are associated with both obesity and T2DM." (PMID 29564328, 2018). "Ethnicity interacted with IGFBP-2 expression in a study from Hawaii; Native Hawaiians with IGFBP-2 expression experienced a greater risk for mortality, but this could be due to the higher rates of obesity in this ethnic group." (PMID 30497427, 2018).
Obesity (continued). "Moreover, the observation that only males on a HFD had decreased IGFBP2 levels could be related to the different susceptibilities of the sexes to develop both obesity and deregulation of glucose metabolism." (PMID 34975768, 2021). "Therefore, the effects of IGFBP-2 on obesity susceptibility and insulin sensitivity are complex and may be influenced by different domains of IGFBP-2 protein." (PMID 30392760, 2019). "Given that obesity is a strong risk factor for breast cancer and potentially also a risk factor for AH in postmenopausal women, it is plausible that IGFBP-2 could confer protection against breast cancer development via inhibition of the adipogenesis that leads to obesity." (PMID 26106415, 2015). "This is in line with existing research, which has highlighted IGFBP‐2 as having a protective role in the development of obesity and metabolic dysfunction." (PMID 41017289, 2025). "Regarding metabolic abnormalities, including NAFLD, low levels of IGFBP-2 have been reported in obesity, type 2 diabetes, and metabolic syndrome, whereas IGFBP-5 is increased in NASH." (PMID 38541155, 2024). "Patients with liver cirrhosis and obesity, showing increased and decreased serum IGFBP-2 levels, respectively, were excluded from the study." (PMID 38255230, 2024). "IGFBP-2 has been extensively studied in obesity, type 2 diabetes, insulin resistance, metabolic syndrome, and as an inductor of cancer." (PMID 38541155, 2024). "Conversely, individuals with T2DM, obesity, or increased visceral fat tend to have lower IGFBP-2 levels compared to healthy lean subjects." (PMID 39585162, 2024). "This shows that the decrease in serum IGFBP-2 in obesity that has been observed in other cohorts is also present in COVID-19 patients." (PMID 38255230, 2024). "While obesity is characterized by low-grade chronic inflammation, evidence consistently shows a decline in circulating IGFBP-2 levels among obese individuals." (PMID 38137505, 2023). "Overexpressing IGFBP-2 has been found to guard against obesity and insulin resistance by inhibiting adipogenesis and enhancing insulin sensitivity." (PMID 38137505, 2023). "Previous studies suggest that IGFBP2 plays a role in diabetes and obesity mainly via regulation of IGFBP1." (PMID 36712921, 2023). "For example, in a diet-induced obesity model, IGFBP2 transgenic mice gained less body weight than the wild-type mice, suggesting that IGFBP2 prevents the development of obesity and insulin resistance." (PMID 37508113, 2023). "Preclinical studies show that IGFBP-2 inhibits adipogenesis and protects against the development of obesity and insulin resistance." (PMID 36686443, 2022). "Taking into consideration that IGFBP2 is a leptin-regulated antidiabetic factor that protects against obesity, we calculated linear correlations between this factor in circulation with insulin, glycemia, leptin, body weight and the percentage of VAT." (PMID 34975768, 2021). "Our proposed mechanism by which IGFBP2 exerts preventive properties in obesity, begins with the ability that IGFBP2 has to prevent and inhibit adipogenesis at local visceral adipose tissue." (PMID 33498859, 2021). "The action of IGFBP2 in obesity appears to act by both dependent (by modulating IGFs) and independent models (through HBD domains) by directly inhibiting adipogenesis and differentiation of preadipocytes at locally visceral adipose tissue." (PMID 33498859, 2021). "Accordingly, great efforts have been carried out to explore the role of IGFBP2 in obesity state and insulin-related diseases, which it is typically found decreased." (PMID 33498859, 2021). "PRKCE has been proven to be a critical DEG in NAFLD, and the expression level and DNA methylation of PRKCE and IGFBP2 were altered in obesity-derived NAFLD." (PMID 34419146, 2021).
Obesity (continued). "IGFBP2 is the second most circulating IGFBP secreted by liver and white adipocytes, and DNA methylation levels are higher in VAT, also SAT but lower compared to VAT, from subject with obesity, indicating a potential implication of IGFBP2 in abdominal obesity." (PMID 33803198, 2021). "IGFBP2 has a significant role in systemic metabolism and as a treatment target in obesity and diabetes." (PMID 34835949, 2021). "The majority of studies reached a consensus idea that serum IGFBP2 is decreased in obesity state, which is observed in different state of obesity and closely related to other anthropometric variables." (PMID 33498859, 2021). "A negative correlation between circulating IGFBP2 and body mass index (BMI) has been reported in obese patients and, in children with obesity, IGFBP2 levels are reduced, whereas in anorexic adolescents they are increased." (PMID 33202914, 2020). "One study on endometrioid endometrial cancer (which is strongly correlated with obesity) showed “increased AMPK phosphorylation and IGFBP2 expression were observed in obese patients with PTEN loss." (PMID 32582754, 2020). "In men with class III obesity, IGFBP2 levels correlated with the grade of hepatic steatosis and disease progression staged by the NAFLD activity score." (PMID 32532003, 2020). "Among the seven IGFBPs, IGFBP-2 is the main binding protein secreted by differentiating white preadipocytes, indicating a potential role in the development of obesity." (PMID 32380764, 2020). "IGFBP-2 is the main IGF-binding protein associated with regulating body weight and homeostasis and protects against obesity and insulin resistance." (PMID 32586279, 2020). "Collectively, these studies provide promising evidence for a potential therapeutic strategy of increasing IGFBP-2 levels to prevent obesity and diabetes." (PMID 30392760, 2019). "Consistently, IGFBP-2 has direct effects on the pathogenesis of obesity and has a positive therapeutic potential." (PMID 30392760, 2019). "Circulating levels of IGFBP-2 are suppressed in obese individuals, an effect which is more linked to visceral adiposity, suggesting a novel role of IGFBP-2 in obesity prevention." (PMID 31547433, 2019). "We provide data that support the idea that C/EBP-α, FOXO1, PPAR-γ2 and IGFBP-2 in visceral adipose tissue are related to obesity-related insulin resistance." (PMID 31547433, 2019). "Because of the known involvement of Igfbp2 in obesity and fat accumulation and due to the 7-fold increase in its mRNA expression in VIS high cells, we sought to determine its role in adipogenesis." (PMID 31597091, 2019). "Low-serum levels of IGFBP-2 are correlated with obesity, metabolic syndrome, and type 2 diabetes, whereas overexpression of IGFBP-2 protects against diabetes and obesity." (PMID 29422987, 2017). "At younger ages, overexpression of mouse IGFBP‐2 increased gonadal fat mass, whereas overexpression of human IGFBP‐2 in mice blocked the development of age‐related obesity later in life." (PMID 26507795, 2016). "In this study, we elucidated the potential role of IGFBP-2 in diet-induced obesity or diabetic mice." (PMID 27009398, 2016). "Circulating IGFBP-2 levels are correlated with metabolic dysfunction including obesity, diabetes, and insulin resistance as Igfbp-2 gene expression is lower in obese and diabetic patients." (PMID 27009398, 2016). "Plasma levels of IGFBP2 are known to inversely correlate with obesity/body mass index (BMI), and insulin resistance." (PMID 25774149, 2015). "Beside their bone anabolic activities, IGFBP2 and Wnt10b are also known for their anti-obesity activities." (PMID 24810249, 2014). "Obesity is associated with insulin resistance and hyperinsulinemia, which reduce the levels of insulin-like growth factor binding protein 1 (IGFBP-1) and insulin-like growth factor binding protein 2 (IGFBP-2)." (PMID 24587258, 2014).